NUTM2B-AS1 (NUTM2B antisense RNA 1)
Synonyms: OPML1
Gene: Long non-coding RNA gene on chromosome 10 (79,661,394 to 79,826,594, reverse strand). Ensembl gene ENSG00000225484.
Diseases named in the same sentence as NUTM2B-AS1 in open-access papers:
NUTM2B-AS1 is named in the same sentence as 1 disease in open-access papers, as found by Europe PMC text mining. Sharing a sentence is not in itself a finding about the gene and the disease.
NUTM2B-AS1 shares sentences with these, for which no sentence is quoted: Leukoencephalopathy (1 paper).